SLC22A20P (solute carrier family 22 member 20, pseudogene)
Description:
Organic anion transporter that mediates the uptake of estrone sulfate. Inhibited by probenecid, propionate, 2-methylbutyrate, 3-methylbutyrate, benzoate, heptanoate and 2-ethylhaxanoate. May act as an odorant transporter (By similarity).
Synonyms: OAT6; FLJ16331; formerly SLC22A20
Gene: Transcribed unitary pseudogene on chromosome 11 (65,213,873 to 65,242,086, forward strand). Ensembl gene ENSG00000197847.
Subcellular location: Membrane